SIRT6 (sirtuin 6)
Diseases named in the same sentence as SIRT6 in open-access papers (continued):
Sharing a sentence is not in itself a finding about the gene and the disease.
lung adenocarcinoma (5 papers, 2019 to 2025). A carcinoma that arises from the lung and is characterized by the presence of malignant glandular epithelial cells. "Here, we found that high expression of SIRT6 is associated with poor prognosis of lung adenocarcinoma, especially in EGFR-mutated NSCLC patients." (PMID 35915188, 2022). "In this study, we used bioinformatics techniques to find that high expression of SIRT6 is associated with poor prognosis of lung adenocarcinoma." (PMID 35915188, 2022). "In the present study, we found that high expression of SIRT6 is associated with poor prognosis of lung adenocarcinoma." (PMID 35915188, 2022). "Given that EGFR-sensitive mutations account for more than half of lung adenocarcinomas, we next investigated whether SIRT6 is also involved in the TKI resistance mechanism associated with poor prognosis in these patients." (PMID 35915188, 2022). "In addition, high expression of SIRT6 is associated with poor prognosis in NSCLC patients, and SIRT6 knockdown increases the sensitivity of lung adenocarcinoma cell lines to paclitaxel." (PMID 35915188, 2022).
lymph node metastasis (5 papers, 2018 to 2022). "In univariable analyses, age, tumor size, stage, histologic grade, lymph node metastasis, distant metastasis, and SIRT6 expression were significantly associated with OS or RFS." (PMID 33198792, 2020). "Age, tumor size, stage, lymph node metastasis, distant metastasis, histologic grade, and SIRT6 expression were included in multivariable analyses." (PMID 33198792, 2020). "NFKBP65 and SIRT6 were significantly correlated with lymph node metastasis regardless of radiation." (PMID 33066317, 2020).
multiple myeloma (5 papers, 2019 to 2024). "SIRT6 is a NAD+ dependent enzyme that is highly expressed in myeloma cells and associated with adverse prognosis." (PMID 31139207, 2019). "The mechanism by which SIRT6 operates in myeloma depends in part on the downregulation of the mitogen-activated protein kinase (MAPK) pathway." (PMID 31139207, 2019). "Myeloma’s DDR is also regulated via epigenetic mechanisms, as recently shown by studies on the role of the histone deacetylase, SIRT6 (sirtuin 6), in genomic stability control." (PMID 31139207, 2019).
neuroblastoma (5 papers, 2008 to 2024). Neuroblastoma (NB) is the most common solid, extracranial childhood tumor. "A study has demonstrated that SIRT6-induced autophagy also contributed to oxidative stress-induced neuronal damage in human neuroblastoma cell line SH-SY5Y cells, indicating that the neuroprotective or neurotoxic role of SIRT6 might depend on cell type." (PMID 35562171, 2022). "We next examined whether the effects observed with SIRT1, SIRT2, SIRT3, SIRT5, and SIRT6 on the regulation of LK-induced neuronal death extended to mouse HT-22 cells, a hippocampally-derived neuroblastoma cell line." (PMID 19116652, 2008). "Expression of SIRT3 promotes apoptosis in neuroblastoma cells and enhances HCA lethality, whereas SIRT6 does not induce HT-22 cell death." (PMID 19116652, 2008).
pancreatic ductal adenocarcinoma (5 papers, 2017 to 2024). An infiltrating adenocarcinoma that arises from the epithelial cells of the pancreas. "A more specific metastasis suppressive role has been described for the (NAD)+‐dependent HDAC SIRT6 in pancreatic ductal adenocarcinoma; the effects of SIRT6 loss seem to be largely mediated through induction of the RNA‐binding protein Lin28b." (PMID 27756687, 2017). "Lower expression of SIRT6 is known to suppress the proliferation of human pancreatic ductal adenocarcinoma (PDAC) cells via histone deacetylation." (PMID 39342193, 2024). "The histone deacetlylase (HDAC) sirtuin 6 (SIRT6) has been shown to act on the LIN28B locus to remove K3K9ac/56ac motifs, decreasing LIN28B expression and suppressing pancreatic ductal adenocarcinoma." (PMID 37370851, 2023).
thyroid cancer (5 papers, 2019 to 2025). "SIRT6 is also linked to ferroptosis resistance in thyroid carcinoma." (PMID 41463311, 2025). "SIRT6 plays a predominantly oncogenic role in thyroid cancer." (PMID 41463311, 2025). "CCDC26 promotes thyroid cancer malignant progression via miR-422a/EZH2/Sirt6 axis." (PMID 36045445, 2022). "In our previous research, we demonstrated SIRT6 interacted with HIF-1α in thyroid cancer cells." (PMID 33436551, 2021). "This is a study infirmed SIRT6/HIF-1α axis in thyroid cancer for the first time." (PMID 30675128, 2019). "SIRT6 has been reported to have multiple roles in previous studies of different tumors, but there is currently no report on thyroid cancer." (PMID 30675128, 2019).
alcoholic liver diseases (4 papers, 2021 to 2025). A disorder caused by damage to the liver parenchyma due to alcohol consumption. "Specifically, it has been reported that the upregulation of the Sirt6/Nrf2 pathway ameliorated alcoholic liver disease and APAP-induced hepatotoxicity via protecting against oxidative stress." (PMID 36978961, 2023). "Furthermore, Sirtuin 6 (SIRT6), a NAD-dependent histone deacetylase which is a critical epigenetic regulator in alcoholic liver disease, deacetylates Smad family member 3 (Smad3) and attenuates its expression induced by transforming growth factor β (TGF-β) in the activated HSCs." (PMID 33791228, 2021).
amyotrophic lateral sclerosis (4 papers, 2022 to 2025). Amyotrophic lateral sclerosis (ALS) is a neurodegenerative disease characterized by progressive muscular paralysis reflecting degeneration of motor neurons in the primary motor cortex, corticospinal tracts, brainstem and spinal cord. "On the other hand, decreased SIRT6 expression has been found in the spinal cord of amyotrophic lateral sclerosis (ALS) patients, enhancing the activity or expression of SIRT6 abrogates its neurotoxicity in cell culture models of ALS." (PMID 36111151, 2022).
asthma (4 papers, 2021 to 2025). "Together, these data indicated that SIRT6 deficiency was important for protecting against airway inflammation and remodeling in severe asthma via the downregulation of mesenchymal reprogramming and airway inflammation." (PMID 38135684, 2023). "Although SIRT6 has been implicated in the development of various diseases, its role in airway inflammation and remodeling in severe asthma is unclear." (PMID 38135684, 2023). "Here the authors show that the epigenetic regulator epithelial sirtuin 6 (Sirt6) is associated with lung inflammation in asthma patients and that Sirt6 contributes to promotion of inflammation in mouse asthma models." (PMID 38135684, 2023). "Enhanced SIRT6 alleviates airway remodeling by modulating epithelial–mesenchymal transition in asthma." (PMID 41008562, 2025). "To dissect how SIRT6 exerts its function in severe asthma, we generated mice with airway epithelium cell-conditional knockout of Sirt6 (AE-Sirt6Δ/Δ)." (PMID 38135684, 2023). "In the subgroup, the SIRT6 levels were higher in patients with severe asthma than those in control individuals and mild to moderate asthmatic patients." (PMID 38135684, 2023). "To investigated the potential mechanisms of SIRT6 in airway remodeling in severe asthma, we first performed RNA sequencing (RNA-seq) for the airway tissues from wild-type (WT) mice exposed to normal saline or HDM/LPS." (PMID 38135684, 2023). "Collectively, these results uncover a function for SIRT6 in regulating IL-17A pathogenicity in severe asthma, implicating SIRT6 as a potential therapeutic target for severe asthma." (PMID 38135684, 2023). "Deletion or inhibition of SIRT6 results in impaired IL-17A secretion in airway epithelium and ameliorates airway remodeling in severe asthma via RORγt-K192 deacetylation." (PMID 38135684, 2023). "In severe asthma patients, high expression of SIRT6 positively correlates with airway remodeling and disease severity." (PMID 38135684, 2023). "Here we identify epithelial sirtuin 6 (SIRT6) as an epigenetic regulator that governs IL-17A pathogenicity in severe asthma." (PMID 38135684, 2023). "Collectively, these results indicated that elevated epithelial SIRT6 promoted IL-17A release, which induced MMPs and cytokines (eg, Mmp3, Mmp12, and Cxcl1) scretion in severe asthma." (PMID 38135684, 2023). "Besides SIRT1, other sirtuins including SIRT2, SIRT3, SIRT6, and SIRT7 have also been linked with asthma." (PMID 41008562, 2025). "Altogether, these data revealed that SIRT6 was increased during asthma and correlated with disease severity and may be a potential biomarker for severe asthma." (PMID 38135684, 2023). "Our data indicated that SIRT6 inhibition might represent a valuable therapeutic approach for severe asthma." (PMID 38135684, 2023). "Together, these data support the therapeutic hypothesis that blocking SIRT6 could prevent IL-17A-mediated airway inflammation and remodeling in severe asthma." (PMID 38135684, 2023). "We further investigate whether SIRT6 regulates the EMT process in severe asthma by modulating airway inflammation." (PMID 38135684, 2023). "In conclusion, we identified epithelial SIRT6 to be an important positive regulator of IL-17A secretion in severe asthma, in which it positively regulated airway inflammation and remodeling mainly throug IL-17A-mediated inflammatory chemokines and mesenchymal reprogramming." (PMID 38135684, 2023). "In the present study, using various human samples (eg, airway biopsy samples, bronchoalveolar lavage fluid [BALF], peripheral blood) and different mouse models of severe asthma, we identify epithelial SIRT6 as an important epigenetic regulator for IL-17A secretion during severe asthma progression." (PMID 38135684, 2023). "However, the expression of Sirt6 mRNA and protein was significantly up-regulated in the peripheral blood and bronchial biopsies of patients with asthma compared with those seen in healthy controls." (PMID 38135684, 2023).
asthma (continued). "Thus, our study disclosed a role for SIRT6 in regulating IL-17A pathogenicity in severe asthma, implicating SIRT6 as a potential therapeutic target for severe asthma." (PMID 38135684, 2023). "Collectively, these data revealed that SIRT6 was highly expressed in airway epithelium cells and potentially promoted asthmatic airway remodeling, which also prompted us to further explore the precise role of epithelial SIRT6 in the airway remodeling process in severe asthma." (PMID 38135684, 2023). "Increased epithelial SIRT6 expression was positively correlated with the severity of asthma." (PMID 38135684, 2023). "Thus, our findings suggested that inhibition of SIRT6 may be of potential value in the treatment of airway remodeling and inflammation in severe asthma." (PMID 38135684, 2023). "Both studies suggest that SIRT6 may serve as a new target for the treatment of asthma." (PMID 36117172, 2022). "Conversely, increased SIRT7 facilitates airway remodeling in asthma by modulating TGF-β1-driven proliferation and migration of airway smooth muscle cells; suggesting a distinct role for SIRT6 in airway remodeling." (PMID 41008562, 2025). "SIRT6 and SIRT7′s expression levels have been elevated in human bronchial epithelial cells which were obtained from asthma patients." (PMID 41008562, 2025). "By using Spearman correlation analysis, the Sirt6 levels were correlated negatively with forced expiratory volume in 1 second (FEV1) (r = −0.41, P = 0.015) and asthma control test (ACT) score (r = −0.39, P = 0.023)." (PMID 38135684, 2023). "Morever, we assessed the efficacy of SIRT6-targeted therapy with a inhibitor OSS had effects on the restoration of airway remodeling via inhibiting IL-17A-mediated mesenchymal reprogramming and airway inflammation in acute and chronic experimental asthma." (PMID 38135684, 2023). "To assess the role of SIRT6 in the pathogenesis of asthmatic airway remodeling, we initially detected the expression of SIRT6 and other sirtuin deacetylases (SIRT1-SIRT5, SIRT7) in the lung tissues in an experimental model of acute severe asthma (ASA)." (PMID 38135684, 2023). "Additionally, some studies have shown that Sirt6 attenuates the EMT process in some diseases, such as suppressing the TGF-β1/Smad3 pathway and c-Jun in an asthma model or inactivating the TGF-β1/Smad2 pathway in bronchial epithelial cells." (PMID 34122724, 2021). "In acute and chronic severe experimental asthma models, we found that both genetic and pharmacological inhibition of SIRT6 attenuated the parameters of airway remodeling, including EMT, myofibroblast transition, and ECM, suggesting that SIRT6 is involved in the pathogensis of severe asthma." (PMID 38135684, 2023). "However, whether and how SIRT6 regulates IL-17A pathogenicity in severe asthma has not been deciphered." (PMID 38135684, 2023).
autoimmune disease (4 papers, 2020 to 2022). A disorder resulting from loss of function or tissue destruction of an organ or multiple organs, arising from humoral or cellular immune responses of the individual to their own tissue constituents. "According to previous reports, only SIRT1, SIRT6, and rarely SIRT7 in the sirtuin family have been associated with dermatologic issues, such as skin aging, skin inflammation, autoimmune disease, cutaneous infection/cancer, and inherited dermatologic disease." (PMID 34122721, 2021). "Overall, our results provide a rationale for further exploring SIRT6 inhibition as a strategy to treat MS or other autoimmune disorders by virtue of its effects on the DC compartment." (PMID 32736564, 2020). "Our goal was to determine the effect of pharmacological Sirt6 inhibition in DC in EAE as a model of autoimmune disorders." (PMID 32736564, 2020). "In addition, TEC conditional knockout of Sirt6 results in severe autoimmune disease manifested by reduced body weight, the infiltration of lymphocytes and the presence of autoantibodies." (PMID 33869219, 2021). "The impaired TRA expression and the poor nTreg cell maturation in Sirt6 cKO mice may lead to the failure of establishing central immune tolerance, which subsequently contribute to the development of autoimmune disease in Sirt6 cKO mice." (PMID 33869219, 2021). "Impressively, TEC-specific Sirt6 knockout mice spontaneously developed autoimmune disease." (PMID 33869219, 2021). "Therefore, Sirt6 might represent a valuable target for developing novel therapeutic agents for the treatment of early stages of MS, or of other autoimmune disorders." (PMID 32736564, 2020). "Therefore, Sirt6 might represent a valuable target for developing novel therapeutic agents for the treatment of the early stages of MS or of other autoimmune disorders." (PMID 32736564, 2020). "On the other hand, we have found that 8-month-old Sirt6 cKO mice, rather than age-matched wild-type mice, have substantial lymphocytic infiltrates in multiple organs and obvious autoantibodies in the serum, indicating that Sirt6 deficient in mTECs leads to autoimmune disorders." (PMID 33869219, 2021).
Cachexia (4 papers, 2017 to 2025). Severe weight loss, wasting of muscle, loss of appetite, and general debility related to a chronic disease. "To determine if pharmacological activation of SIRT6 would similarly inhibit cachexia‐associated adipose lipolysis, we used MDL800, a selective agonist of SIRT6, to treat adipocytes." (PMID 39971710, 2025). "Ten‐week‐old SIRT6 transgenic (TG) and wild type (WT) male mice injected with LLC cells (1.5 × 106 per mouse) were used to investigate the protective effects of SIRT6 on cachexia‐associated adipose browning and lipolysis and the underlying mechanisms." (PMID 39971710, 2025). "In summary, findings of our study strongly suggest that skeletal muscle‐specific over‐expression of SIRT6 at a moderate level restricts tumour progression and alleviates associated cachexia by regulating diverse targets." (PMID 34212132, 2021). "Previously, it was observed that mice deficient in a chromatin‐bound lysine deacylase, SIRT6, exhibited a phenotype analogous to cachexia with loss of skeletal muscle and fat tissue as well as extensive inflammation and perturbed energy metabolism." (PMID 34212132, 2021). "Our previous study has demonstrated that by attenuating NF‐κB binding to Mstn promoter, SIRT6 downregulates myostatin expression and muscle loss in in vitro models of cachexia." (PMID 34212132, 2021). "SIRT6 knockout (SIRT6-KO) mice display loss of muscle, fat and bone density, typical characteristics of cachexia." (PMID 28928419, 2017). "We found an unexpected beneficial function of SIRT6 in cancer cachexia, demonstrating that increased SIRT6 expression or activity is capable of protecting the host against cachexia‐associated tissue wasting, providing a concept of future therapies for cachexia." (PMID 39971710, 2025). "Thus, our data suggest that SIRT6 attenuation of cachexia‐associated adipose lipolysis through the suppression of TNFR2." (PMID 39971710, 2025). "We show that circulating SIRT6 levels are negatively associated with cachexia in cancer patients." (PMID 39971710, 2025). "We sought out to identify possible targets through which muscle‐specific SIRT6 over‐expression might exert a paracrine effect to normalize perturbed metabolism in cancer‐associated cachexia." (PMID 34212132, 2021). "The ability of SIRT6 to act as a tumour suppressor and to help promote muscle health prompted us to explore whether skeletal muscle‐specific over‐expression of SIRT6 in mice could limit the destructive consequences of cancer‐associated cachexia." (PMID 34212132, 2021). "In this study, we demonstrate that SIRT6 ameliorates WAT dysfunction and helps prevent cancer‐associated cachexia." (PMID 39971710, 2025). "Although at this point, we cannot precisely predict on how SIRT6 promotes expression of GLUT4 in muscle, our results suggest that SIRT6 over‐expression in skeletal muscle likely mitigates cancer‐induced cachexia by preserving whole body glucose homeostasis." (PMID 34212132, 2021). "Given the multifactorial nature of cachexia, SIRT6, which concurrently controls multiple pathways, can be a valuable therapeutic target to overcome this debilitating syndrome." (PMID 34212132, 2021). "We believe that in our cancer‐cachexia model, SIRT6 over‐expression by maintaining α‐TUBULIN levels likely preserves normal microtubule organization in skeletal muscle and thereby supports muscle mass." (PMID 34212132, 2021). "In relevance to cachexia, our recent study shows that SIRT6 was able to downregulate expression of myostatin (MSTN), a member of the transforming growth factor (TGF)‐β family and a known potent negative regulator of skeletal muscle mass." (PMID 34212132, 2021). "Mice depleted of SIRT6 phenotypically resemble a condition akin to cachexia with extensive metabolic problems, inflammation and increased energy expenditure." (PMID 28928419, 2017).